RN7SL716P (RNA, 7SL, cytoplasmic 716, pseudogene)
Gene: Miscellaneous RNA gene on chromosome 17 (59,059,226 to 59,059,493, forward strand). Ensembl gene ENSG00000263558.
Homologues: Orthologues: chimpanzee Metazoa_SRP (99% identical), macaque Metazoa_SRP (45% identical). Paralogues in human: RN7SL377P (78% identical), Metazoa_SRP (77% identical), Metazoa_SRP (75% identical), RN7SL279P (75% identical), RN7SL850P (75% identical), Metazoa_SRP (74% identical), RN7SL155P (74% identical), RN7SL32P (74% identical), RN7SL48P (74% identical), Metazoa_SRP (73% identical), RN7SL202P (73% identical), RN7SL356P (71% identical), and 706 more.